NOTCH1 (notch receptor 1)
Diseases named in the same sentence as NOTCH1 in open-access papers (continued):
Sharing a sentence is not in itself a finding about the gene and the disease.
lung adenocarcinoma (48 papers, 2012 to 2025). A carcinoma that arises from the lung and is characterized by the presence of malignant glandular epithelial cells. "In this study, we investigated the effects of functional Notch1 deficiency in an autochthonous KrasLSL-G12V driven lung adenocarcinoma mouse model." (PMID 34257546, 2021). "After Notch1 ablation in vivo, there is a dramatic decrease in tumor initiation and burden in a mouse model of lung adenocarcinoma, demonstrating that Notch1 is implicated in the initiation, proliferation and survival of NSCLC models in preclinical studies." (PMID 29416684, 2018). "Collectively, these mouse model studies clearly show a prooncogenic role for NOTCH1 in lung adenocarcinoma development within a KRAS-mutated cellular context." (PMID 26491213, 2015). "Considering the role of the Notch pathway in promoting epithelial-to-mesenchymal transition (EMT), we conducted a comprehensive analysis to explore the association between NOTCH1 expression and the metastatic characteristics of lung adenocarcinoma (LUAD) patients across multiple studies." (PMID 39737401, 2024). "NOTCH1 is a gene encoding a transmembrane protein that plays an important role in tumorigenesis, and NOTCH1 mutations are frequently detected in colon adenocarcinoma, lung adenocarcinoma, and breast invasive ductal carcinoma." (PMID 37864465, 2024). "In lung adenocarcinoma, fluctuations in NOTCH1 activity are mainly caused by mutations, post-translational modifications, and truncations that may drive the transition from an epithelial to a mesenchymal phenotype, which leads to the increased metastatic ability of the cancer cell." (PMID 41451346, 2025). "Taken together, disruptions in NOTCH1 signaling play a key role in the progression of lung adenocarcinoma by modulating normal cellular communication, promoting tumor development, invasiveness, and metastasis, and possibly contributing to drug resistance." (PMID 41451346, 2025). "This interference in NOTCH1 signaling can disrupt normal cellular functions, such as differentiation and stem cell-like properties, and promote tumorigenesis and progression in lung adenocarcinoma." (PMID 41451346, 2025). "CTC counts correlated to tumor progression in patients with early lung adenocarcinoma and successfully detected typical mutant genes (Notch1, IGF2, EGFR, and PTCH1) and genes in smokers as predictive biomarkers." (PMID 37371825, 2023). "Notch1 also mediates chemoresistance and strengthens the proliferative capacity of lung adenocarcinoma cells through the negative regulation of miR-451 by the transcription factor AP-1." (PMID 34717617, 2021). "Both Notch1 and TAZ are overexpressed in lung adenocarcinoma and associated with poor prognosis in lung adenocarcinoma patients." (PMID 34482375, 2021). "The function of Notch1 in glycolysis in lung adenocarcinoma at least partly explains the inhibited expression of glycolytic genes induced by Notch1 knockdown." (PMID 34482375, 2021). "More importantly, we found that miR-153 inhibited stem cell-like phenotype and tumor growth of lung adenocarcinoma through inactivating the Jagged1/Notch1 axis." (PMID 32375892, 2020). "Under normal oxygen concentrations, the proliferation of lung adenocarcinoma cells can be inhibited by blocking the Notch1 signaling pathway." (PMID 33138076, 2020).
lung adenocarcinoma (continued). "mRNA expression corresponding to Notch1 was significantly elevated in peripheral CD4+ T cells purified from lung adenocarcinoma patients in comparison with those from NCs (approximately five-fold induction, P<0.0001)." (PMID 30473538, 2018). "The current data indicated that elevated Notch1 induced higher IL-22 secretion by CD4+ T cells in lung adenocarcinoma patients, and Notch-AhR-IL-22 axis took part in the pathogenesis of lung adenocarcinoma." (PMID 30473538, 2018). "In conclusion, elevated Notch1 induced higher IL-22 secretion by CD4+ T cells in lung adenocarcinoma patients, and Notch-AhR-IL-22 axis took part in the pathogenesis of lung adenocarcinoma." (PMID 30473538, 2018). "Notch-1 overexpression was found in T-cell leukemias and Notch1 pathway is activated in different tumors such as lung adenocarcinoma." (PMID 28415812, 2017). "The high expression levels of the NOTCH1 and NOTCH3 genes have been observed to be significantly associated with poor prognosis in lung adenocarcinoma." (PMID 28422717, 2017). "The current study demonstrates HDAC6 is required for activation of Notch-1 signaling in response to TGF-β1 in human lung adenocarcinoma cells." (PMID 27499032, 2016). "In support of such an idea, studies from several groups have shown that NOTCH1 is required for lung tumorigenesis in genetically engineered mouse models of lung adenocarcinoma that commonly express mutant KRAS." (PMID 26491213, 2015). "Notch1 was originally found to be overexpressed in T-cell leukemias as the result of an oncogenic translocation, and since then, the Notch1 pathway has been shown to be activated in multiple tumor types, including lung adenocarcinomas." (PMID 23671619, 2013). "In conclusion, these experiments provide mechanistic evidence that the Notch1 pathway is activated in lung adenocarcinoma cells in response to PTE treatment to enhance the survival of cancer cells." (PMID 23671619, 2013). "The expression of Notch1 protein in the lung adenocarcinoma group was significantly higher compared with the normal lung group (P<0.01), as shown by western blot analysis." (PMID 23420695, 2013). "In this study, we investigated the antitumor activities of PTE against human lung adenocarcinoma in vitro and in vivo and the role of the Notch1 signaling pathway in these activities." (PMID 23671619, 2013). "In this study, we investigated the antitumor activity of PTE against human lung adenocarcinoma in vitro and in vivo and explored the role of the Notch1 signaling pathway in this process." (PMID 23671619, 2013). "Studies have shown that components of the Notch1 pathway are overexpressed during the progression of lung adenocarcinoma, as observed for other genes involved in the survival of cancer cells." (PMID 23671619, 2013). "The aim of this study is to detect the expression of Notch-1 and analyze its clinicopathological or prognostic significance in different histological subtypes of Lung Adenocarcinomas (LADs)." (PMID 24423157, 2013). "Notch signaling promotes cell survival, and the increment in Notch1 activity promotes tumor growth in lung adenocarcinoma when cultured under hypoxic conditions." (PMID 23071601, 2012). "Activated NOTCH1 induced lung adenomas in mice and cooperated with Myc in the generation of lung adenocarcinoma." (PMID 22539939, 2012). "The critical drivers of the EMT signaling pathway are Snail, Slug, and Twist, which may have been influenced by NOTCH signaling, and dysregulated NOTCH1 signaling in lung adenocarcinoma can, therefore, drive EMT and subsequent metastasis." (PMID 41451346, 2025). "We found that NOTCH1 was frequently up-regulated in some cancers including colon adenocarcinoma, kidney renal clear cell carcinoma and esophageal carcinoma, whereas the expression of NOTCH1 was significantly down-regulated in kidney renal papillary cell carcinoma and lung adenocarcinoma." (PMID 36119057, 2022).
lung adenocarcinoma (continued). "In addition, we used data from TCGA to show that putative inactivating NOTCH1 mutations co-occur with KRAS mutations and genomic amplifications in lung adenocarcinomas." (PMID 34257546, 2021). "Notch1 is overexpressed and promotes tumor growth in lung adenocarcinoma." (PMID 34482375, 2021). "Similarly, the enrichment of CD133+ cells in lung adenocarcinoma after cisplatin induction leads to multidrug resistance through activation of Notch signaling as higher levels of cleaved Notch1 (NICD1) are detected." (PMID 29681949, 2018). "In lung adenocarcinoma, IGF-1R overexpression and Akt activation by NOTCH1 is stimulated by hypoxic microenvironment, and NOTCH1 targeting may provide a viable therapeutic approach for patients with K-Ras mutant lung adenocarcinoma." (PMID 27980227, 2017). "Under the condition of hypoxia, Notch-1 could be activated by HIF1α (hypoxia-inducible factor 1-α) in lung adenocarcinoma cells, then the activated Notch-1 could suppress the expression of PTEN (phosphatase and tensin homolog) and activate AKT." (PMID 28977931, 2017). "The down-regulation of Notch1 signaling sensitizes lung adenocarcinoma cells to PTE treatment." (PMID 23671619, 2013). "In summary, lung adenocarcinoma cells may enhance Notch1 activation as a protective mechanism in response to PTE treatment." (PMID 23671619, 2013). "Notch1 also stimulates survival of lung adenocarcinoma cells." (PMID 23651443, 2013). "NOTCH1 nonsynonymous mutations were associated with class-switched and IgA B cells in BRCA ER+ tumors (estimate = 10.6, adjusted P = 0.003), and nonsynonymous mutations in DGRC8 were associated with enriched IgA B cells in lung adenocarcinoma (estimate = 18.7, adjusted P = 0.04)." (PMID 39966644, 2025). "Moreover, hypoxia via HIF1α stabilizes and activates Notch1 in lung adenocarcinomas." (PMID 25653136, 2015). "Moreover, Notch1 expression predicted not only less progressive disease but also better overall survival in lung adenocarcinoma patients Taken together, Notch1 plays distinct roles depending on its activation status in patients with all stages of NSCLC from I to IV." (PMID 25653136, 2015). "Therefore, we propose that the inhibition of Notch1 signaling may be a novel strategy to prevent the induction of cancer survival mechanisms in advanced lung adenocarcinomas." (PMID 23671619, 2013). "Inhibited Notch1 decreased cell invasiveness and partially reversed EMT in lung adenocarcinoma cells." (PMID 36882799, 2023). "Notch1 mRNA expression was significantly elevated in CD4+ T cells purified from peripheral bloods and tumor site BALF in lung adenocarcinoma patients." (PMID 30473538, 2018). "NICD1 was found to directly bind to the SOX9 gene promoter elements and to activate its transcription, demonstrating a molecular mechanism by which NOTCH1 drives EMT and invasion in lung adenocarcinoma cells." (PMID 26491213, 2015). "In this study, our data suggest that Notch1 signalling is frequently overexpressed in human NSCLC, including stage I lung adenocarcinomas." (PMID 23651443, 2013). "AGRN directly interacts with NOTCH1 and increases the release of Notch intracellular structural domain 1 (NICD1), leading to the activation of the Notch pathway, which promotes the proliferation, migration and invasion of lung adenocarcinoma cells." (PMID 41340014, 2025). "It was also shown that NOTCH1 can be activated by ADAM10 (A Disintegrin and metalloproteinase domain-containing protein 10), a sheddase with α-secretase activity, and promoted migration and invasion of the A549 lung adenocarcinoma cells." (PMID 26491213, 2015).
lung adenocarcinoma (continued). "Spheres derived from the lung adenocarcinoma cell line, H1299, exhibited a contraction of the S-phase of the cell cycle compared with monolayer cultures, consistent with a non-replicating state, and enrichment of the stemness markers KLF4, Notch-1, Nanog and Sox2." (PMID 29651165, 2018). "Furthermore, it has been shown that gefitinib-acquired resistant lung adenocarcinoma cells undergo EMT by activation of Notch-1 signaling via Notch-1 receptor intracellular domain (N1IC), the activated form of the Notch-1 receptor." (PMID 29681949, 2018). "However, there were no remarkable differences in Notch1 mRNA expression in either peripheral or BALF CD4+ T cells between EGFR mutation and non-EGFR mutation lung adenocarcinoma patients (P=0.852 and 0.403, respectively)." (PMID 30473538, 2018). "However, the relationship between Notch1 activation and the sensitivity of tumor cells to cytotoxic agents in lung adenocarcinoma has not been examined." (PMID 23671619, 2013). "In addition, obviously higher expression of oncogenes c-MYC, WNT1, WNT2, and NOTCH1 was detected in side population (SP) cells than in non-side population (NSP) cells of human lung adenocarcinoma cell line-A549, revealing a possible mechanism for the tenacious tumorigenic potential of CSCs." (PMID 22615765, 2012). "In the present study, we found that Notch1 mRNA, but not Notch2 mRNA, was elevated in both peripheral and lung-resident CD4+ T cells in lung adenocarcinoma patients." (PMID 30473538, 2018). "In A549 lung adenocarcinoma cells exposed to cadmium, HIF1α has been shown to upregulate the expression level of the intracellular domain (ICD) but not the transmembrane subunit (NTM) of NOTCH1, and the regulation is independent of the HIF1α transcriptional activity." (PMID 33015064, 2020).
non-small cell lung carcinoma (47 papers, 2012 to 2026). A group of at least three distinct histological types of lung cancer, including non-small cell squamous cell carcinoma, adenocarcinoma, and large cell carcinoma. "In human non-small-cell lung cancer, the gain-of-function mutation of the Notch1 gene and the weakening of the pathway due to the loss of NUMB have been described." (PMID 36644230, 2023). "Recent studies of delta-tocotrienol on non-small cell lung cancer discovered that the anticancer activity induced by delta-tocotrienol is associated with its ability to decrease Notch-1, Hes-1, Survivin, MMP-9, VEGF, and Bcl-XL expressions, with additional decrease of binding activity in NF-κB-DNA." (PMID 25480449, 2014). "This is consistent with recent studies reporting autophagy promotion upon cycloastragenol treatment through the AMPK/ULK1/mTOR pathway in human non-small-cell lung cancer lines or via Notch1 signaling in human keratinocytes." (PMID 41596421, 2026). "In non-small-cell lung cancer, high expression of NOTCH1 enhances tumor proliferation and lymphatic metastasis." (PMID 35897085, 2022). "Low levels of IFN γ-induced stemness in a dose-dependent manner to activate the ICAM-PI3K-Akt-Notch1 axis in non-small cell lung cancer." (PMID 36550571, 2022). "Further exploration demonstrated that circNOTCH1 can compete with NOTCH1 mRNA for METTL14 binding to increase NOTCH1 mRNA stability, eventually promoting tumor growth, in non-small-cell lung cancer." (PMID 35701841, 2022). "On the other hand, recent literature confirmed the inhibiting role of Notch1 in non-small cell lung cancer." (PMID 32547317, 2020). "It is known that radiation can induce Notch1 activation in breast CSCs and non-small cell lung cancer cells to confer radioresistance." (PMID 30678233, 2019). "Rajasinghe and Gupta showed that tocotrienol-rich mixture hindered cell proliferation, migration, and tumor cell invasiveness by downregulating NF-κB and Notch-1 pathways during apoptosis induction in non-small cell lung cancer cells (NSCLC)." (PMID 30717416, 2019). "For example, in a non-small cell lung cancer model, Notch2 mediates differentiation and has tumor suppressor function, whereas Notch1 promotes tumor initiation and progression." (PMID 29963552, 2018). "Studies have shown that the overactivity of Notch and the increased expression of Notch1 and Hes1 proteins may indicate a poor prognosis of non-small cell lung cancer." (PMID 38544826, 2024). "The O-methylated flavonol rhamnetin and the natural flavonoid cirsiliol overcame radioresistance via the downregulation of Notch1, Ciap1, Ciap2, survivin, vimentin, and fibronectin and the up-regulation of E-cadherin in radio-exposed non-small cell lung cancer cells." (PMID 37240422, 2023). "Moreover, RECK suppresses cancer stem cells (CSCs) self-renewal and maintenance via mediating the activation of Notch1 signaling regulated by miR-221/22 in non-small cell lung cancer." (PMID 37904179, 2023). "The aim of this study is to study the mechanism of chlorogenic acid on apoptosis of nonsmall lung cancer through Notch1 pathway in animal level, and hope to provide theory basis on clinical treatment and research aimed at targeting Notch1 signaling in non-small cell carcinoma (NSCLC)." (PMID 28855037, 2017). "Additionally, aberrant expression of NOTCH1 is found in various types of human cancers, including non-small cell lung cancer." (PMID 24621612, 2014). "In addition, a previous study also revealed that activation of Notch1 was enhanced in non-small cell lung cancer cells cultured with Delta-like 4-expressing endothelial cells, thus inhibiting the proliferation of non-small cell lung cancer cells and tumor formation." (PMID 34988077, 2021).
non-small cell lung carcinoma (continued). "In non-small cell lung cancer (NSCLC), Notch1 and Notch2 function mainly as oncogenes, while Notch3 facilitates NSCLC development and progression." (PMID 41050674, 2025). "In non-small-cell lung cancer, IL-10 derived from M2 macrophages promotes cancer stemness through the JAK1/STAT1/NF-κB/Notch1 pathway." (PMID 36838713, 2023). "It has also been reported that in non-small cell lung cancer (NSCLC), resistant to radiotherapy, the expression of Nrf2 and NOTCH1 increases synergistically." (PMID 35906617, 2022). "In human patients with non-small cell lung cancer, ADAM10 overexpression activated the Notch1 signaling pathway, leading to increased cell migration and invasion." (PMID 33535178, 2021). "This was in congruence with previous studies where cirsiliol along with rhamnetin downregulated Notch-1-mediated radio-resistance and EMT phenotypes in non-small cell lung carcinoma cell lines." (PMID 30708951, 2019). "In the mechanism of non-small-cell lung cancer (NSCLC), NSCLC cell growth is dependent on NOTCH1." (PMID 39452835, 2024). "In addition, overexpression of SLC6A8 promotes proliferation, migration, and invasion of non-small cell lung cancer, accompanied by upregulation of MMP9 and activation of the NOTCH 1 signaling pathway." (PMID 37234174, 2023).